CXCR4 (C-X-C motif chemokine receptor 4)
Diseases named in the same sentence as CXCR4 in open-access papers (continued):
Sharing a sentence is not in itself a finding about the gene and the disease.
ovarian carcinoma (continued). "Furthermore, it was further confirmed by cell experiments that SDF-1/CXCR4 may promote cell proliferation, migration, invasion, and inhibition of apoptosis to make ovarian cancer cell progress, which indicates that the expression changes of SDF-1/CXCR4 are related to ovarian cancer progress." (PMID 35545781, 2022). "CXCR4 participates in the EOC development, is expressed by ovarian cancer, tumor and stromal cells (myeloid or T cells), and cooperates with angiogenic factors to generate new vessels." (PMID 35406620, 2022). "In a syngeneic ovarian cancer model, locoregional delivery of the oncolytic vaccinia virus (OVV)-plus CXCR4 antagonist (CXCR4-A) reduced the tumor load and promoted the immune response through CD103 + dendritic cells." (PMID 35406620, 2022). "CXCR4 is also a therapeutic target for the FDA approved antagonist, Plerixafor, that has been suggested as a complementary treatment for ovarian cancer." (PMID 35145271, 2022). "The overexpression of PGE2 in the microenvironment of ovarian cancer also induces the production of CXCL12 (SDF1), thereby enhances the migration of CD11b+CD14+CD33+CXCR4+MDSCs to the ascites of patients with ovarian cancer." (PMID 34689842, 2021). "The results showed that the expression of CXCR3, CXCR4, and CXCR7 mRNA in ovarian cancer tissues was significantly higher than that in normal ovarian tissues (P < 0.05)." (PMID 33829065, 2021). "In ovarian cancer, CXCL12/CXCR4 signaling stimulated tumor angiogenesis, development of cancer-initiating cells and metastasis to the peritoneum via recruitment of immunosuppressive cells, such as regulatory T (Treg) cells." (PMID 34503058, 2021). "In ovarian cancer cells, CXCL12 and its receptor CXCR4 increased the production of integrin-1β and vascular endothelial growth factor-C (VEGF-C), activating tumor vasculature in ovarian cancer." (PMID 34912809, 2021). "By contrast, metastases of ovarian cancer to omentum involve predominantly CXCR1 and CXCR4 is necessary for leukemic cells dissemination to SAT and VAT." (PMID 33671469, 2021). "Combinatorial blockade of CXCR4 and PD-1 reduces Tregs and MDSCs recruitment within the immunosuppressive TME promoting tumor-specific cell-mediated immune responses in ovarian cancer." (PMID 33937018, 2021). "The results of the HOUP hub genes confirmed that the expression levels of TNF, ESR1, CDK1, CXCR4 and MUC1, indicating these 5 hypomethylated genes were activated in ovarian cancer development." (PMID 32192517, 2020). "An CXCR4 antagonist AMD3100 reduced the intratumoral Tregs content and recruited T-helper cells in a mouse model of ovarian cancer." (PMID 33096815, 2020). "In a mouse model of ovarian cancer, AMD3100 treatment showed significant increases in T-cell–mediated antitumor immune responses, resulting in CXCR4 positive tumor apoptosis and necrosis." (PMID 33363463, 2020). "Downregulation of CXCR4 also resulted in a robust reduction of the circulating ovarian cancer cells, suggesting a possible role of the SDF1/CXCR4 axis in the hematogenous route of dissemination." (PMID 31888563, 2019). "The cross-talk between CXCL12-activated CXCR4 and EGFR was suggested to play an important role in cell proliferation signaling in ovarian carcinoma cell lines." (PMID 31703453, 2019). "In depth, the functional expression of CXCR4 in IGROV and CAOV-3 ovarian cancer cells were demonstrated by the presence of CXCL12-induced Ca2+ transients." (PMID 31703453, 2019). "The Notch pathway has also been found to promote ovarian cancer growth and migration via the CXCL12/CXCR4 chemokine system." (PMID 31382985, 2019). "Recent studies showed that CXCR4+/CD133+ cells, isolated from ovarian cancer cell lines, display properties of tumor-initiating cells, including phenotypic and functional properties." (PMID 29389895, 2018).
ovarian carcinoma (continued). "The expression of SDF1 is positively correlated with CXCR4 in epithelial ovarian cancer, in which both SDF1/CXCR4 are involved in cell malignant transformation and take part in the development, invasion and metastasis of ovarian malignancies." (PMID 29783989, 2018). "The promotion of antitumor immunity by CXCR4-antagonists was reported for a mouse model of ovarian cancer and in an orthotopic preclinical hepatocellular carcinoma (HCC) model where a CXCR4 antagonist was combined with a checkpoint inhibitor." (PMID 30622535, 2018). "The activation of CXCR4 results in the upregulation of the prometastatic cytokines IL-6, CXCL12, and TNFα in ovarian cancer cells and increases metastasis." (PMID 28275576, 2017). "Mifepristone at concentrations < IC50 inhibited expression of CXCR4 on cell surface of ovarian cancer SKOV-3 and IGROV-1, and reduced expression of the intracellular CXCR4 protein and its related mRNA activated by SDF-1." (PMID 28938623, 2017). "AMD3100 (1 μg/ml), a well-documented CXCR4 antagonist, inhibited cell proliferation in the presence of SDF-1, and verified the function of the SDF-1/CXCR4 axis in the tested ovarian cancer cells." (PMID 28938623, 2017). "In ovarian cancer (OVC) cells, the SDF-1/CXCR4 axis is mediated by the vascular endothelial cell growth factor, endolyn, Notch pathway, and nuclear factor of activated T-cells 3 transcription factor." (PMID 28196146, 2017). "Our studies also showed that SDF-1/CXCR4 axis is involved in EMT of various cancers including lung, pancreatic, hepatic, and ovarian cancers." (PMID 28196146, 2017). "Through suppression of CXCR4 expression, mifepristone down-regulated the intracellular expression of Akt, ERK, p-Akt and p-ERK in ovarian cancer cell lines." (PMID 28938623, 2017). "Chemokine signature of a panel of 29 human ovarian cancer cell lines showed dominant expression of CXCL1-3, 8 and CXCR4." (PMID 27723802, 2016). "CXCR4 expression was low (ranging from 0% to 62.5%, median 2.4%) and CD133 level was even lower (ranging from 0% to 48%, median 1.25%) in the fresh ovarian cancer cells." (PMID 26020117, 2015). "Accordingly, CD133+CXCR4+ OVCAR5 sorted cells were evaluated for sensitivity to cisplatin, a commonly used agent for the treatment of ovarian cancer, and for the expression of ABCG2, a surface transporter associated with resistance to chemotherapy." (PMID 26020117, 2015). "The same dual effect of genistein was observed for the C-X-C chemokine receptor type 4 (CXCR4) and C-X-C motif chemokine 12 (CXCL12) levels in breast and ovarian cancer cells." (PMID 26703550, 2015). "We compared the mRNA expression of CXCR3, CXCL-10, CXCR4, CXCL-12, IL-4, and IL-10 in tissues of benign and malignant ovarian tumors by qRT-PCR method and evaluated serum IL-10 and CA-125 content of these patients by ELISA during one year." (PMID 25999622, 2015). "In the current study, we performed a comparative analysis on mRNA expression of CXCR3, CXCL-10 (IP-10), CXCR4, CXCL-12 (SDF-1α), IL-4 (interleukine-4) and IL-10 in tissues of benign and malignant ovarian tumors by the qRT-PCR method." (PMID 25999622, 2015). "Ovarian cancer cell lines and tumor biopsies have been shown to express elevated levels of IL-6, TNF, CXCL12, and its receptor CXCR4, and expression of these is co-regulated." (PMID 24936477, 2014). "The present study aimed to characterize the expression pattern and levels of SDF-1, CXCR4 and CXCR7 in normal human ovaries and epithelial ovarian cancer." (PMID 24765189, 2014). "A recent study demonstrated that all 289 ovarian cancer patients analyzed expressed CXCL12, and the rate of CXCR4 expression was 69%; thus CXCL12 can serve as an independent prognostic indicator for ovarian cancer." (PMID 24765180, 2014).
ovarian carcinoma (continued). "Frequencies of MDSCs closely correlated with CXCL12 and PGE-2 levels in ascitic fluid, and inhibition of COX-2 or PGE-2 receptors in MDSCs suppressed CXCR4 expression, and thus MDSC responsiveness to CXCL12 or ovarian cancer ascites." (PMID 23508517, 2013). "Along with CXCR4, the CXCR6 receptor and its ligand CXCL16 were reported to be significantly upregulated in ovarian cancers compared to the normal ovarian epithelium or benign ovarian tumors." (PMID 24384839, 2013). "We used this imaging reporter to analyze CXCL12-CXCR4 signaling in ovarian cancer and establish that AMD3100, a small molecule inhibitor of CXCR4, blocks receptor activation in the tumor microenvironment." (PMID 23372646, 2013). "We also confirmed that CD164 had the ability to increase the CXCR4 and CXCR7 mRNA levels in some ovarian cancer cells." (PMID 24094005, 2013). "For example, a cross talk between CXCL12-activated CXCR4 and epidermal growth factor receptor (EGFR) has been proposed to link cell proliferation signals in ovarian carcinoma." (PMID 24384839, 2013). "Various tumours, in particular the androgen-dependent tumours such as prostate, breast and ovarian cancers, produce CXCL12 and express CXCR4." (PMID 22415233, 2012). "In this same ovarian cancer model, IL-2 treatment was shown to up-regulate CCR4 as well as CXCR4, which further enhanced the ability of Treg to migrate to the tumor microenvironment based on its elevated levels of the Treg ligands CCL22 and CXCL12." (PMID 22112546, 2011). "Thus, even if the published studies individually examined a small number of ovarian cancers, all these results agree that CXCL12/CXCR4 axis may be closely associated with the development of peritoneal metastasis and the prognosis of patients with epithelial ovarian carcinoma (EOC)." (PMID 20049170, 2010). "Similar to our previous work with the chemoprotective phytochemical, 3,3′-diindolylmethane (DIM), we show here that genistein also downregulates CXCR4 and CXCL12 and subsequently lowers the migratory and invasive potentials of breast and ovarian cancer cells." (PMID 19325924, 2009). "To get some insight into the functionality of CXCR4 receptors on the surface of ovarian cancer cells, we included an analysis of SDF-1 on the cell membrane – the only known soluble ligand of CXCR4." (PMID 17245339, 2007). "When CXCR4 expression was reduced, there was a notable decrease in the number of circulating ovarian cancer cells, indicating that the SDF1/CXCR4 pathway might also be involved in blood-borne dissemination." (PMID 40109727, 2025). "Using orthotopically grown SV40 T antigen+ ovarian carcinoma in antigen-naive wild-type or TgMISIIR-TAg-Low transgenic mice expressing SV40 T antigen as a self-antigen, we investigated the impact of CXCR4-antagonist-armed oncolytic virotherapy on tumor progression and antitumor immunity." (PMID 36875325, 2023). "Over-expressed CXCR4 enhances proliferation and invasion of cancer cells through positive regulation of EMT via CXCR4/CXCL12 signaling, stimulates cellular stemness and chemo-resistance, and in consequence worsens PFS in ovarian cancer patients." (PMID 38248751, 2023). "The simultaneous inhibition of the CXCR4—SDF-1 and PD-1—PD-L1 pathways and the depletion of effector Tregs may enhance the antitumor immune response and reduce mortality in ovarian cancer patients." (PMID 36831623, 2023). "Of note, the phosphorylated form of CXCR4 has not yet been part of a study regarding carcinomas of the ovary." (PMID 35397601, 2022). "For inhibition of the recruitment of TAMs, the CCL2/CCR2 axis barricade which is has been found to be helpful in a mouse ovarian cancer model, and disrupting the CXCL12/CXCR4 axis which prolongs the survival of a tumor mouse model seem to be an encouraging therapy." (PMID 36341388, 2022).
ovarian carcinoma (continued). "In a mouse model of intraperitoneal ovarian cancer, compared with single drug therapy of AMD3100 (CXCR4 antagonist) and αPD-1, the antitumor efficacy of combined therapy in inhibiting tumor growth and prolonging the survival time of mice was significantly improved." (PMID 36341388, 2022). "However, there are different results showing that CXCR4/CXCL12 axis promotes EMT and is a potential target of ovarian cancer progression." (PMID 33829065, 2021). "CXCR7 does not play a key role in EMT, but CXCL12/CXCR4 axis is a potential target for preventing ovarian cancer progression." (PMID 33829065, 2021). "Overexpression of CXCR4 can promote the proliferation and invasion of ovarian cancer cells, while the inhibitor AMD3100 and shRNA silencing CXCR4 can inhibit epithelial-mesenchymal transition, thereby inhibiting tumor proliferation, metastasis, and cell activation." (PMID 33829065, 2021). "Moreover, CXCR4, IFNG, IL24, MTMR14, and RB1 all exhibited higher expression in ovarian cancer compared to normal specimens." (PMID 33748162, 2021). "In ovarian cancer, tumor-related MSCs were able to induce resistance to hyperthermic intraperitoneal chemotherapy by activating the CXCL12-CXCR4 axis, and when the CXCL12/CXCR4 interaction was blocked, the cytotoxicity of hyperthermia was restored." (PMID 34736460, 2021). "In ovarian cancer cells, CD164 was localized in the cytosol and nucleus suggesting that nuclear CD164 might regulate CXCR4 promoter activity." (PMID 32719743, 2020). "Once the presence of EpCAM positive CTCs in the blood of patients was confirmed using two methodologies, an expression profile analysis, including a panel of genes related to cell plasticity and ovarian cancer aggressiveness (MUC1, CK19, CXCR4, TIMP1, ALDH1, CD24, CD44, GDF1), was carried out." (PMID 32423054, 2020). "In CAOV-3 cells, CXCL12 and its receptor CXCR4 stimulated the secretion of integrin β-1 and vascular endothelial growth factor-C (VEGF-C), indicating the involvement of this receptor in the stimulation of tumor vasculature in ovarian cancer." (PMID 31703453, 2019). "For example, CXCR4 inhibition with AMD3100 treatment led to increased T cell-mediated antitumor activity with concomitant reduction of Tregs, which resulted in improved survival in ovarian cancer and melanoma immunocompetent mouse models." (PMID 30420856, 2018). "The human ovarian cancer cell lines (pre-spreading in vitro) showed dominant expression levels of CXCL1-3, 8 and CXCR4, while EOC (post-spreading in vivo) had higher levels of CCL20, CXCL17 and CXCR4." (PMID 27723802, 2016). "CXCR4 and CD133 expression identified a discrete population with stem cell properties in human ovarian cancer cells that might be critical for tumor development and chemo resistance." (PMID 26020117, 2015). "CXCR4 had been proved to be upregulated in many cancers, including RCC and ovarian cancer." (PMID 26526157, 2015). "Moreover, OVCAR-5 CXCR4+CD133+ cells migrated toward the CXCR4 ligand CXCL12, were less sensitive to the most popular chemotherapeutic agent utilized in ovarian cancer, cisplatin, and over expressed the drug resistance transporter ABCG2." (PMID 26020117, 2015). "Cancer cells overexpressing CXCR4 and CD133 were evaluated in fresh primary human ovarian cancer revealing extremely variable levels of CXCR4+/CD133+ and CD24+/CD44+ positive cells, without significant differences among the group of patients." (PMID 26020117, 2015). "Even in our studies, we saw differences between Jurkat T-cell leukemia and HeyA8 ovarian cancer cell lines with regards to phospho-ERK levels and CXCR4 surface expression levels, further illustrating the stark differences in regulation and signaling between cell types." (PMID 25514788, 2014).
ovarian carcinoma (continued). "The expression of CXCR4 and CXCL12 was increased in the ovarian cancer cells in a dose- and time-dependent manner when treated with LPA compared with the control groups (P<0.05), as determined by reverse transcription polymerase chain reaction and flow cytometry." (PMID 24765180, 2014). "Also those ovarian cancer cells with a high endogenous expression of TNF, expressed higher levels of CXCR4 than cells with a low TNF expression." (PMID 23800251, 2013). "In addition to direct effects on ovarian cancer cells, CXCL12 and CXCR4 regulate key components of the tumor microenvironment." (PMID 23372646, 2013). "Mice treated with AMD3100 or the combination of AMD3100 and cisplatin had significantly lower bioluminescence from CXCR4-CBRN and Ar-CBC complementation relative to overall tumor burden, showing that this drug successfully blocks CXCR4 signaling in ovarian cancer cells in vivo (p<0.01)." (PMID 23372646, 2013). "To model the tumor microenvironment of ovarian cancer in vivo, we used spheroids of HeyA8-CXCR4-CBRN/Ar-CBC cells combined with equal numbers of HeyA8-CXCL12-GL cells, reproducing human ovarian cancer in which tumor cells secrete CXCL12 and/or express CXCR4." (PMID 23372646, 2013). "Because both BRMS1 and CXCR4 are involved in regulating the NF-κB signaling pathway, we hypothesized that BRMS1 might modulate metastasis of ovarian cancer cells in part by regulating CXCR4 expression." (PMID 22200669, 2012). "Using a tissue microarray of 289 primary ovarian cancers coupled to a comprehensive database of clinicopathological variables, the expression of CXCL12 and CXCR4 was assessed by immunohistochemistry and its impact in terms of survival and clinicopathological variables was determined." (PMID 22415233, 2012). "The ligand for CXCR4 is CXCL12, which can stimulate ovarian cancer cells migration in vitro." (PMID 22022379, 2011). "However, in consideration that 91% and 59% of ovarian cancers express CXCL12 and CXCR4, respectively, it was proposed that an overexpression of this chemokine system was present in ovarian malignant cells." (PMID 20049170, 2010). "Subsequently, CXCR4 and CXCL12 expression in ovarian cancer have been confirmed by other studies." (PMID 20049170, 2010). "Neither the cytoplasmatic nor the nuclear CXCR4 expression was correlated with the HER2/neu expression in ovarian cancer tissues (data not shown)." (PMID 17245339, 2007). "Besides the upstream signaling of HIF-1α, the downstream effectors of HIF-1α might also be involved in the ovarian cancer malignancy, namely, C-X-C motif chemokine ligand 12 (CXCL12) and C-X-C motif chemokine receptor 4 (CXCR4)." (PMID 36207479, 2023). "The results showed that similar to the stimulation of ovarian cancer organoids, the proportions of CD11b+, CD66b+, and ICAM-1+ neutrophils in each case of neutrophils were significantly increased after MUC16 treatment for 24 h, while the proportions of CXCR4+ neutrophils were decreased slightly." (PMID 37644468, 2023). "However, the prognostic value of CXCR4 in ovarian cancer remains controversial and has not been emphasized." (PMID 24658065, 2014). "However, CXCR4 expression was unchanged when PI3K pathway was blocked suggesting the increase in CXCR4 expression in HeyA8 ovarian cancer cell line is mainly dependent on the MEK-ERK pathway and not the PI3K pathway." (PMID 25514788, 2014). "Elevated CXCR4 mRNA expression has recently been reported in ovarian cancer; however, this particular study lacked important information regarding the oligonucleotide sequences applied and failed to include measurements of the resultant CXCR4 protein expression." (PMID 24765189, 2014). "Thus, angiogenesis in ovarian cancer may be potentiated by the interaction of CXCL12 produced by the cancer cells and CXCR4 expressed by the endothelial cells in hypoxic conditions." (PMID 24384839, 2013).